VHL (von Hippel-Lindau tumor suppressor)
Diseases named in the same sentence as VHL in open-access papers (continued):
Sharing a sentence is not in itself a finding about the gene and the disease.
tumor (continued). "Expression of non-hydroxylatable Beclin1 P54A abrogates VHL-mediated autophagy inhibition and significantly reduces the tumor-suppressing effect of VHL." (PMID 38360997, 2024). "Our results on the VHL regulation of PIK3R3 mRNA stability support our observation of decreased PIK3R3 in patients with ccRCC, which is further confirmed by our PIK3R3 IHC staining results in ccRCC tumor and normal tissues." (PMID 38618952, 2024). "Therefore, genes that regulate the expression of VHL and its downstream targets are involved in modulating tumor-induced hypoxia and ECM remodeling of tumor cells." (PMID 39886373, 2024). "Notably, the 3p chromosome change impacts over 500 genes, featuring tumor suppressors like BAP1, FHIT, VHL, PTPγ, SEMA3B, SEMA3F, TUSC2, and MLH1." (PMID 39201328, 2024). "The VHL-defective lesions arising in the kidneys of VHL patients demonstrate an increase in HIF and HIF target genes, and mouse VHL–/– ccRCC xenograft experiments revealed a tumor-promoting role of HIF2α and a tumor-constraining role of HIF1α." (PMID 38360997, 2024). "In VHL-knockout RCC cell lines, AKT is activated, promoting cell survival and tumor development." (PMID 39748950, 2024). "The remarkable phenotypic heterogeneity in organ involvement and tumor onset age between and within VHL families has not allowed reliable markers to predict the age-related tumor risks in VHL patients." (PMID 39272694, 2024). "In a recent study, we reported that spontaneous metastasis in ccRCC models requires the presence of and cross communication between two distinct tumor cell populations, one that does not express any pVHL (VHL-Neg) and one that expresses WT pVHL (VHL-Pos)." (PMID 37762376, 2023). "VHL(−) exosomes even induced a complete cascade of distant metastasis when added to VHL(+) tumor xenografts in a duck chorioallantoic membrane (dCAM) model, while VHL(+) exosomes did not." (PMID 38139136, 2023). "Moreover, low VHL mRNA levels showed a strong correlation with patients’ older age, advanced clinical stage of the disease, classical PTC histovariant, and tumor multifocality." (PMID 36036061, 2023). "The PNET tumor tissue revealed no somatic mutations, but the RCC tissue harbored somatic mutations in ERBB2, VHL, and PTEN." (PMID 37007151, 2023). "Analysis of human ccRCC tumor #22 revealed the same pattern, with the Ki67 positivity rate more than seven times higher in the VHL-positive (26.6%) than the VHL-negative tumor areas (1.4%)." (PMID 37069149, 2023). "Son of patient II-1 and genetically diagnosed of VHL at 11 years old, asymptomatic and without tumours at the time of diagnosis." (PMID 37843608, 2023). "Indeed, pharmacological suppression of VEGF in different VHL−/− ccRCC cell lines impairs xenograft growth in nude mice, implicating VEGF as a potent tumor-promoting gene in ccRCC." (PMID 36831657, 2023). "When VHL is genetically inactivated, HIF1α and HIF2α become stabilized, which leads to changes in cellular metabolism, angiogenesis, epithelial-mesenchymal transition (EMT), invasion, and tumor metastasis that contribute to the progression of ccRCC." (PMID 37190141, 2023). "The CRISPR/Cas9-mediated biallelic deletion of VHL gene in the VHL+ primary tumor cells of case #22, designated as #22 VHL-KO cells, was confirmed by DNA sequencing (data not shown)." (PMID 37069149, 2023). "VHL samples are more similar in their expression profile to sporadic rather than Cluster 1A tumours indicating a high degree of similarity after dimensionality reduction." (PMID 38124114, 2023). "Moreover, the protein expression levels of VHL and HIF‐1α in tumor tissues collected from xenograft tumor models were detected by IHC, and the results were similar to those from western blotting." (PMID 37563971, 2023). "Due to a lack of data on the tumor growth of VHL-related pNETs, no recommendations for the ideal timing of pNETs can be made." (PMID 37251595, 2023).
tumor (continued). "Tumor analysis revealed protein markers consistent with VHL-driven tumorigenesis and pVHL." (PMID 35304467, 2022). "In our study, multivariable models were adjusted for underlying clinical characteristics, which leads us to believe that the protective effects on CSS we observe for mutations in VHL and PBRM1 are independent of underlying tumour characteristics." (PMID 35444164, 2022). "Combined with existing literature, VHL and PBRM1 may also be significantly related to the tumor progression of KIRC and may be used in immunotherapies for treating KIRC." (PMID 35846133, 2022). "Here, the tumor suppressor GSK3β phosphorylates HIF-1α at three serine residues within the human HIF-1α N-terminal transactivation domain, which results in the Fbw7 and USP28-mediated HIF-1α ubiquitination and VHL-independent proteasomal degradation." (PMID 36699028, 2022). "More importantly, through the co-analysis of our data and the Clinical Proteomic Tumor Analysis Consortium (CPTAC) study of ccRCC, 57 proteins were identified that are ubiquitinated and downregulated by VHL restoration in 786-O and overexpressed in ccRCC clinical samples." (PMID 35159281, 2022). "In addition, up to 80% of ccRCC have the inactivated VHL gene which leads to HIF-α accumulation and the activation of HIF target genes which promote tumor angiogenesis, invasion, metabolic reprogramming, and metastasis." (PMID 35110537, 2022). "However, hypoxia or an irregularity in VHL renders pVHL ineffective; this leads to the stabilization of HIF-α, which activates the expression of several target genes that facilitate tumor progression." (PMID 35625561, 2022). "ccRCC can be considered a metabolic disease, since loss of chromosome arm 3p and inactivation of the Von‐Hippel Lindau (VHL) tumour suppressor and the resultant constitutively active hypoxia‐inducible factor (HIF) transcription factor in the majority of tumours lead to marked metabolic changes." (PMID 35678045, 2022). "Furthermore, UBE2S was demonstrated to be negatively correlated with the von Hippel-Lindau tumor-suppressor (pVHL), which mediated the ubiquitin-dependent proteolysis of HIF1A, in multiple tumor cell lines." (PMID 36138435, 2022). "Tumor-elicited inflammation is caused by the activation of oncogenes, which lead to cytokine production and tissue remodeling, and by the inactivation of tumor suppressor genes (e.g., PTEN, VHL) that also regulate production of inflammatory factors and cytokines." (PMID 35086565, 2022). "The relative mRNA levels of VHL showed a marked reduction in 24 out of the 30 tumours, which were not suspected by the data of gene copy numbers." (PMID 35586183, 2022). "In the patient without VHL mutation, we found alterations in CUL3, DOT1L, SETD2 and TSC1 in the primary tumor, with the addition of BAP1 gene mutation in its analyzable PMs." (PMID 34885018, 2021). "DT2216, a first-in-class selective BCL-XL degrader, is reported to target tumor cells more selectively as it targets BCL-XL to the Von Hippel-Lindau (VHL) E3 ligase for proteasomal degradation; platelets have minimal expression of VHL." (PMID 34073507, 2021). "Furthermore, proline hydroxylation is important for the tumour suppression activity of DYRK1 toward the regulation of VHL E3 ligase activity and hence, the stability of VHL substrates critical for cell cycle progression such as HIF-2α, AURKA, and cyclin D1." (PMID 34062959, 2021). "VHL is dysfunctional or inactivated in over 80% of ccRCC, resulting in increased HIF activity and overexpression of VEGF and PDGF which contributes to uncontrolled angiogenesis and tumour growth." (PMID 34527581, 2021).
tumor (continued). "We demonstrated that the protein level of VHL-R167Q, which has the functional capacity to downregulate HIF-2α, interferes with the transcription of genes belonging to cancer cell stemness and tumor plasticity pathways in 786-0 R167Q cells, as compared with 786-0 EV cells." (PMID 34359798, 2021). "According to studies, the first miRNA could act a tumour suppressor in RCC cell lines via the targeting c-MYC, while the second one is a VHL-regulated tumour suppressor acting through hindering macroautophagy." (PMID 35008576, 2021). "In this sense, VHL-mediated HIF-1α and HIF-2α stabilization blunts the differentiation of CD8 T cells in vitro but increases GZMB expression, promoting the capacity of these cells to control tumor growth and persistent viral infections." (PMID 34025660, 2021). "Exosomal miR-23 suppresses the expression of VHL to upregulate HIF-1α, GLUT-1, vascular endothelial growth factor (VEGF) and subsequently triggers the proliferation, metastasis, 5-FU resistance and other malignant biological behaviors of tumor cells." (PMID 33869059, 2021). "Recovered tumor cells contained a reduced amount of VHL–12VC1.2 compared with that in the starting cells prior to injection and that of the negative control degrader in the recovered tumor cells." (PMID 33976200, 2021). "The other thesis states that tumours with VHL alterations may represent ccRCC with morphology and immunoprofile closely mimicking that of ccpRCC and RAT tumours." (PMID 35008576, 2021). "Due to the special characteristics of RCCs in VHL patients, tumor control aims to prevent metastatic disease, which is unlikely to occur in tumors < 3 cm." (PMID 34414496, 2021). "Positive mutation status was accompanied by an increase in NF-κB p65, NF-κBp50, VEGF HIF-2 VHL level compared to the primary tumor with negative BRAF-V600E status." (PMID 34319022, 2021). "Hypoxia, a common feature of iron deficiency, has been demonstrated to play a major part in tumor progression and treatment resistance in mice by corrupting the von Hippel-Lindau (VHL) gene, the master regulator of hypoxia-inducible factor (HIF) and thus a tumor suppressor." (PMID 33777027, 2021). "VHL codifies for a tumor suppressor protein involved in the degradation of hypoxia-inducible factor alpha (HIF1α) and the stromal-derived factor-1 receptor (CXCR4) proteins, which leads to the block of angiogenesis and tumor cell migration." (PMID 31903105, 2020). "Due to the lack of functional pVHL in VHL-ccRCC primary tumor cells and in 786-O cells, HIF proteins are not targeted for proteasomal degradation and can accumulate in the cell." (PMID 32854260, 2020). "In VHL patients, the earliest VHL-null multi-cellular renal tubule lesions tend to strongly express HIF-1α and weakly express HIF-2α, but later lesions such as cysts and tumours express HIF-1α as well as higher levels of HIF-2α23,53." (PMID 32807776, 2020). "However, the same VHL knockout RENCA cells had reduced proliferation in vitro when compared to control, and the same primary tumor weight as control after orthotopic injection (despite the fact that VHL is a well-known tumor-suppressor)." (PMID 33077781, 2020). "Another VHL-based ALK PROTAC TD-004 efficiently induced ALK degradation and inhibited the proliferation of SU-DHL-1 and H3122 cells in vitro, and reduced H3122 xenografted tumor growth in vivo." (PMID 32718354, 2020). "We also demonstrate that the infiltration of 22 different types of immune cells into the tumor microenvironment is dependent on the status of PBRM1 mutations and independent of VHL mutations." (PMID 33177244, 2020). "Patients with a family history of VHL must present with CHB, PCC, or ccRCC; however, if there is no family history of disease, patients must then present with two more CHBs or a CHB and a visceral tumour, such as ccRCC." (PMID 33151962, 2020).
tumor (continued). "Both the lack of negative feedback compared to that exerted by normal VHL and the upregulation mediated by tumor hypoxia explain these higher levels of RSUME." (PMID 30890701, 2019). "During tumour progression, VEGF-B and VHL decrease, while HIF1a increases." (PMID 31337000, 2019). "VHL expression was significantly lower in RCC patients with a higher tumor grade, whereas LC3B expression was significantly higher in RCC patients with a higher tumor grade." (PMID 30902965, 2019). "VHL inhibits the induction of various target molecules of HIFs, such as vascular endothelial growth factor (VEGF) and platelet-derived growth factor (PDGF), by forming a complex (BVC) with elongin B/C and Cullin2, thereby exerting its tumor suppressor effect." (PMID 30902965, 2019). "Lack of degradation of this factor due to the absence of the VHL protein results, for instance, in an uncontrolled production of factors promoting blood vessel formation (e.g., VEGF) and is implicated in tumour development." (PMID 31443481, 2019). "In the TCGA data, neither LBD nor tumour prominence were related to VHL expression (also not within D3 or M3 cases), stressing the importance of tumour genetics over tumour size for VHL levels as well." (PMID 31323773, 2019). "PeriFN suppresses tumor progression could further be evidenced by the fact that, in von Hippel-Lindau (VHL) disease, defected pVHL protein gives rise to renal tumorigenesis where periFN assembly is hampered." (PMID 31861892, 2019). "Regardless of its abundance in the VHL tumor, a dysfunctional HIF1α was consistent with the oncocytic phenotype and its benign nature." (PMID 30728892, 2019). "Other studies also reported mutations and gene variations either directly in immune system-related genes, such as PD-1, PD-L1, IDO, and VEGF, or in tumor suppressor genes such as TSC2 and VHL, along with transcriptional upregulation of oncogenic pathways in patients with HPD." (PMID 31683809, 2019). "In RCC cells, MALAT1 was positively regulated by VHL pathway through c-FOS transcription factor and promoted EMT features of tumor cells in a PRC2-dependent manner, since EZH2 depletion inhibited MALAT1-dependent tumor-promoting activity." (PMID 29739426, 2018). "Of the other 29 patients included in our study, VHL mutations were distributed without clustering throughout all 3 exons of the VHL tumor suppressor gene." (PMID 30214643, 2018). "Under hypoxic conditions, as well as in case of VHL inactivation, HIF-1α is stabilised and accumulates in the nucleus leading to subsequent over-expression of genes which are critical for tumour angiogenesis, glucose transport, epithelial proliferation, cell migration, and pH control." (PMID 29251173, 2018). "A higher mRNA expression of the HIF1 (but not HIF2) target genes, GLUT1 and HK2, was reported in VHL-mutated compared to SDHB-mutated adrenal medulla tissue, and VHL-mutated tumours demonstrate increased glycolysis in comparison to SDHx-derived PPGL." (PMID 29450727, 2018). "We found an identical VHL gene sequence in 100% of the CCC and corresponding tumor samples from the 20 patients, including two patients harbouring wild type VHL sequences in their CCC and corresponding tumor samples." (PMID 29732003, 2018). "VHL is a tumor suppressor in ccRCC that regulates its substrates by forming a complex with elongins B and C (termed “VBC”), which are key components of an E3 ubiquitin ligase complex that is crucial for VHL function." (PMID 29562667, 2018). "This prompted us to examine whether the remaining major tumor suppressors in ccRCC, SETD2 and BAP1, also regulate ISGF3 in VHL-/-ccRCC cells." (PMID 30355451, 2018). "VHL status in ccRCC does not correlate with clinical outcome; however, it can be described as a classic tumour suppressor protein and has been shown to exert multiple anti-oncogenic functions." (PMID 29463811, 2018).
tumor (continued). "Conversely, NKs derived from VHL-WT patient (#29) did not significantly increase CD107a exposure either toward RCC autologous tumor cells than toward SN12C or A498 cell lines." (PMID 30514329, 2018). "The expression levels of miRNAs miR-99a, 99b, 100; 199a; 106a; 106b; 29a; 29b; 29c; 126; 200a, 200b and their respective target genes: mTOR, HIF1-α, VHL, PDGF, VEGF, VEGFR1 and VEGFR2 were analyzed using qRT-PCR in tumor tissue samples from 56 patients with ccRCC." (PMID 29202733, 2017). "We next measured transcriptional levels of the VHL gene by RT-qPCR (n=36) to compare tumor samples with and without VHLdel." (PMID 28036268, 2017). "The highest number of differentially methylated probes were detected in tumours with NF1-mutations (1651 probes) followed by those without known mutations (1184 probes), those with RET-mutations (432 probes) and those with VHL-mutations (339 probes)." (PMID 28327598, 2017). "To directly test this hypothesis, we evaluated expression of VHL and its signaling axis in our Daam2-GOF and Daam2-LOF mouse tumor models." (PMID 29053101, 2017). "In addition, the level of two TS proteins, VHL and PDLIM4, was increased in SH-I-14-treated tumor samples." (PMID 29137356, 2017). "Some studies have shown that staining patterns differ between tumors and non-tumor tissues or in VHL mutant or non-mutant samples." (PMID 27583351, 2017). "Our results lend further support to the notion that loss of an as yet unidentified locus (or loci) in 11p15 could contribute to tumor formation in SDHD, SDHAF2 and VHL-related PGLs/PCCs." (PMID 28099933, 2017). "This cohort was subdivided into two groups: multiple tumor patients with a combination of PC/PGL/HNPGL + RCC (n = 12 probands; group A) and familial non-VHL RAPTAS cases with RCC or PC/PGL/HNPGL and an FDR with the alternative tumor type (n = 21 patients, 10 probands; group B)." (PMID 28973655, 2017). "Loss of SDHB immunostaining in the PC from case 2 prompted additional sequencing of tumor tissue from the PC and RCC because germline testing did not reveal a germline mutation in SDHx or VHL." (PMID 28973655, 2017). "To avoid any false negative artifacts we paid attention to analyze the VHL sequence of one paraffin embedded ccRCC tissue block that contained at least 70 % tumor cells." (PMID 27530247, 2016). "Previous studies reported reduction of VHL protein, rather than mRNA in VHL-related tumor patients, suggesting that instability of the pVHL protein itself is a primary cause of dysfunction." (PMID 27517496, 2016). "We therefore conclude that most non-mutated tumors were in fact VHL wild type and that the use of more than one FFPE block to analyze one tumor would have not influenced significantly our results." (PMID 27530247, 2016). "Therefore, 3p LOH and frameshift deletion/hypermethylation in VHL led to tumorigenesis of tumor BC_1L, while LOH at 3p segment covering VHL and VHL promoter hypermethylation were two founder drivers for tumor BC_1R." (PMID 27383411, 2016). "Some studies showed that the presence or absence of VHL alterations does not affect tumour stage, grade, or prognosis." (PMID 26448938, 2015). "Defective VHL protein expression leads to stabilization of hypoxia-inducible factors 1and 2, increased DNA damage, and to activation of the PI3K/Akt pathway stimulating cell proliferation and tumor growth." (PMID 26298773, 2015). "All evaluated HCC tissues showed a wild-type VHL gene profile, regardless of tumor differentiation state." (PMID 27119112, 2015). "HHT induced apoptosis in VHL-mutant, but not VHL-reconstituted, ccRCC cells, and inhibited tumor growth in 30% of VHL-mutant patient-derived ccRCC tumorgraft lines tested." (PMID 26219258, 2015). "Although tumours with either mutation in SETD2 or VHL, and both WT status did not change in size following TGX221 treatment, ACHN tumours were in general slightly larger than Caki-1 or 786O tumours." (PMID 25853938, 2015).